IREB2 (iron responsive element binding protein 2)
Diseases named in the same sentence as IREB2 in open-access papers (continued):
Sharing a sentence is not in itself a finding about the gene and the disease.
glioma (3 papers, 2021 to 2024). A benign or malignant brain and spinal cord tumor that arises from glial cells (astrocytes, oligodendrocytes, ependymal cells). "Subsequently, ROC curve analysis suggested that the AUC values of WWTR1, STEAP3, SLC39A14, NOTCH2, IREB2, HIF1A, and FANCD2 were all 1.000, indicating their potential as diagnostic biomarkers for gliomas." (PMID 37978473, 2023). "In conclusion, we identify seven ferroptosis-associated genes (SLC39A14, WWTR1, STEAP3, NOTCH2, IREB2, HIF1A, and FANCD2) in gliomas, all of which are highly expressed." (PMID 37978473, 2023). "Seven ferroptosis-related hub genes, namely SLC39A14, WWTR1, STEAP3, NOTCH2, IREB2, HIF1A, and FANCD2, were identified, all of which were highly expressed in glioma." (PMID 37978473, 2023). "Subsequent analyses prioritized SLC40A1 over IREB2, since IREB2 has no expression or survival significance in glioma." (PMID 39039049, 2024).
intracerebral hemorrhage (3 papers, 2022 to 2024). A cerebrovascular disorder characterized by bleeding into one or both cerebral hemispheres including the basal ganglia and the cerebral cortex. "Ferroptosis is related to the increase of IREB2 that occurred in mice intracerebral hemorrhage, and the exosomes from miR-19b-3p-modified adipose-derived stem cells reduced the expression of Ireb2, alleviated ferroptosis in intracerebral hemorrhage mice, and improved neurological function." (PMID 35720183, 2022).
lung diseases (3 papers, 2015 to 2023). "While the link between IREB2 and pulmonary disease is still unclear, we see at least three potential mechanisms which are not mutually exclusive." (PMID 37228113, 2023). "IREB2 is located in the region near the CHRNA3/CHRNA5/CHRNAB4 genes cluster with a possible role of lung diseases development." (PMID 26310313, 2015). "This approach provided an assessment of the potential role of IREB2 and FAM13A genes in lung disease development in the Polish population." (PMID 26310313, 2015).
schizophrenia (3 papers, 2022 to 2023). A major psychotic disorder characterized by abnormalities in the perception or expression of reality. "IREB2, the main translational repressor for ferritin, was significantly associated with schizophrenia in both CLOZUK and PGC2 genome-wide association studies and survived Mendelian randomization analysis." (PMID 36750734, 2023). "As IREB2 was shown to be marginally overexpressed in schizophrenia PFC, these latter findings could provide a potential link to understanding why ferritin protein levels among patients in our sample were exceptionally low in individuals with below-mean iron content." (PMID 36750734, 2023).
Alzheimer disease (2 papers, 2014 to 2022). A progressive, neurodegenerative disease characterized by loss of function and death of nerve cells in several areas of the brain leading to loss of cognitive function such as memory and language. "IREB2 polymorphisms have also been associated with Alzheimer's disease." (PMID 25120486, 2014).
Ataxia (2 papers, 2014 to 2024). Ataxia refers to impaired coordination of voluntary muscle movement. "Irp2/Ireb2 gene deletion in mice causes a late-onset movement disorder characterized by lower motor neuronal degeneration with significant spinal cord axonopathy, progressive loss of motor capabilities, ataxia, bradykinesia and tremor that progress slowly as the animals age." (PMID 39684697, 2024).
COVID-19 (2 papers, 2024 to 2025). A disease caused by infection with severe acute respiratory syndrome coronavirus 2. "Among patients with COVID-19 symptoms, the CC genotype of the IREB2 rs13180 polymorphism was significantly more frequent (χ2 = 3.95, df = 2, p = 0.05)." (PMID 41007821, 2025). "Furthermore, the CC genotype of the IREB2 rs13180 polymorphism was associated with clinical manifestations of COVID-19 in COPD patients, indicating a potential impact of this genetic variant on susceptibility to viral infections in this population." (PMID 41007821, 2025). "Importantly, our analysis revealed a potential link between the IREB2 rs13180 CC genotype and the presence of clinical manifestations of COVID-19 among COPD patients." (PMID 41007821, 2025).
gastric cancer (2 papers, 2015 to 2024). A primary or metastatic malignant neoplasm involving the stomach. "Then, both HGC27 and HGC27/L cells were treated with different concentrations of baicalin for 24 h to explore the changes of key genes of ferroptosis, such as TfR, FTH1, GPX4 and IREB2 in gastric cancer cells exposed to baicalin with different concentrations." (PMID 38730240, 2024). "Some nonsynonymous mutations caused low levels of gene activity with down-regulation of mRNA expression (ZNF208, CRNN, IREB2 and ACADL), which may be crucial tumor suppressor genes for gastric cancer and may contribute to the extensive dissemination of cancer cells in abdominal cavity." (PMID 26330360, 2015).
Insulin resistance (2 papers, 2020 to 2025). Increased resistance towards insulin, that is, diminished effectiveness of insulin in reducing blood glucose levels. "They found that increased expression of IREB2 in steatotic liver insulin resistance (IR) and SHP-HR led to iron death of hepatocytes and further aggravated liver tissue injury." (PMID 39910919, 2025). "Consistently, a rapid glucose response to insulin load was not evident in HFD-fed rats after overexpressing IREB2, inhibiting insulin sensitivity while increasing the Homeostatic Model Assessment for Insulin Resistance (HOMA-IR) score." (PMID 39910919, 2025).
nicotine addiction (2 papers, 2024 to 2025). "We found genes related to nicotine addiction (CHRNA3, CHRNA4, CHRNA5), neurodegeneration (IREB2), chromosome maintenance (HIST1H2BD), mRNA stability (CSDC2), and transcriptional repression to be potentially affected by the pregnancy maternal smoking phenotype." (PMID 40074595, 2025).
renal carcinoma (2 papers, 2022 to 2025). A carcinoma arising from the epithelium of the renal parenchyma or the renal pelvis. "Here, we report a novel founding that low ACO1 and IREB2 contents in renal cancer are linked to the decreased invasion of B cells, neutrophils, CD4+ T cells, dendritic cells, and CD8+ T cells, along with macrophages." (PMID 36059676, 2022). "Meanwhile, there is a paucity of information about the mechanisms and clinical significance of ACO1 and IREB2 downregulation in renal cancers." (PMID 36059676, 2022). "ACO1 antagonist sodium oxalomalate (OMA) and IREB2 inhibitor sodium nitroprusside (SNP) was used to treat renal cancer ACHN cells together with sorafenib." (PMID 36059676, 2022). "ACO1 and IREB2 downregulation in renal cancers were correlated with cancer aggressiveness, cellular iron homeostasis, cytotoxic immune cell infiltration, and patient survival outcomes." (PMID 36059676, 2022). "The current work focuses on combining several bioinformatics tools to assess if ACO1 and IREB2 are involved in renal cancer development and ferroptosis, as well as their molecular regulation." (PMID 36059676, 2022). "We then wondered if blocking ACO1 and IREB2 action interferes with sorafenib-triggered cell death in renal cancer." (PMID 36059676, 2022). "Weak evidence has revealed the role and clinical aspects of ACO1 and IREB2 in renal cancer at various stages of etiology and prognosis based on the strong relationship between iron homeostasis and carcinogenesis." (PMID 36059676, 2022). "More remarkably, ACO1 and IREB2 regulate the time of survival of individuals with renal cancer partly through immune cell invasion." (PMID 36059676, 2022). "Herein, blocking the activation of ACO1 or IREB2 by its inhibitors OMA or SNP ameliorated sorafenib-triggered cell death, supporting that ACO1 and IREB2 could participate in its cytotoxic influence on renal cancer cells." (PMID 36059676, 2022). "The protein expression level of ACO1 and IREB2 were further investigated in renal cancer using the HPA database, and we noticed that the ACO1 and IREB2 protein level turned evidently down in the tissues of KIRC contrasted with healthy kidney." (PMID 36059676, 2022). "IREB2 stabilizes the mRNA of TFRC and DMT1 that code for iron transporters, leading to increased intracellular iron concentration 63 and is dysregulated in lung 64 and renal cancers." (PMID 40083931, 2025). "As far as we know, the network between ACO1, IREB2 and immune cell invasion in renal cancer has not been clearly studied." (PMID 36059676, 2022).
age-related macular degeneration (1 paper, 2014). Age-related loss of vision in the central portion of the retina (macula), secondary to retinal degeneration. "Finally, polymorphisms in both ACO1 and IREB2 have been linked to age-related macular degeneration." (PMID 25120486, 2014).
alpha 1-antitrypsin deficiency (1 paper, 2012). Alpha-1-antitrypsin deficiency is a hereditary disease that develops in adulthood and is characterized by chronic liver disorders (cirrhosis), respiratory disorders (emphysema), and rarely panniculitis. "IREB2 and CHRNA3 are potential genetic modifiers of COPD phenotypes in individuals with severe AAT deficiency and may be sex-specific in their impact." (PMID 22356581, 2012).
colitis (1 paper, 2025). Inflammation of the colon. "In a DSS-induced colitis model, we observed that activation of the HMGB1/TLR4/NF-kB pathway resulted in decreased GPX4 expression, accompanied by increased mRNA levels of ferroptosis-related indicators (PTGS2, IREB2, CS, RPL8, and ATP5G3), which was further verified by cellular experiments." (PMID 40689397, 2025).
Dystonia (1 paper, 2024). An abnormally increased muscular tone that causes fixed abnormal postures. "The third, a 7-year-old patient, was compound heterozygous for biallelic missense IRP2/IREB2 mutations and developed a disease characterized by profound neurodevelopment delay, seizures, dystonia and choreiform movements." (PMID 39684697, 2024).
lung adenocarcinoma (1 paper, 2015). A carcinoma that arises from the lung and is characterized by the presence of malignant glandular epithelial cells. "However, a quantitative analysis of IREB2 mRNA levels in paired normal lung and lung adenocarcinoma tissue demonstrated the increased expression of CHRNA5, but no change in IREB231." (PMID 26310313, 2015).
multiple sclerosis (1 paper, 2024). A progressive autoimmune disorder affecting the central nervous system resulting in demyelination. "This study identified IREB2, LAMP2, ISCU, ATP6V1G1, ATP13A2, and SKP1 as genes associated with multiple sclerosis (MS) and iron metabolism, establishing their multi-gene diagnostic value for MS with an AUC of 0.83." (PMID 38590521, 2024).
ovarian carcinoma (1 paper, 2023). A malignant neoplasm originating from the surface ovarian epithelium. "The expression of MTF1 and BMP6 involved in iron regulation was associated with improved OS in ovarian cancer, whereas the expression of IREB2, GPI, and HMOX1 in this process was associated with poor OS in ovarian cancer." (PMID 38186569, 2023). "Exploring the iron regulation in ovarian cancer, most genes integral to this process, like IREB2, HFE, BMP6, HMOX1, and ACO1, showed decreased expression compared to their normal tissue counterparts." (PMID 38186569, 2023). "Furthermore, lower expression levels of ACO1, HFE, IREB2, and MTF1 in iron regulation were associated with an advanced stage of ovarian cancer." (PMID 38186569, 2023).
Ovarian cyst (1 paper, 2024). The presence of one or more cysts of the ovary. "The expression of IREB2 positively correlates with CA125 levels and the diameter of ovarian cysts, and negatively correlates with disease staging." (PMID 39872538, 2024).
pulmonary fibrosis (1 paper, 2024). Chronic progressive interstitial lung disorder characterized by the replacement of the lung tissue by connective tissue, leading to progressive dyspnea, respiratory failure, or right heart failure. "Our results demonstrated a considerable increase in IREB2 content in AECII from pulmonary fibrosis mice and BLM-injured MLE-12 cells." (PMID 38773980, 2024). "Our experimental results revealed that protein content of IREB2 were substantially elevated in the AECII of BLM-induced pulmonary fibrosis mice." (PMID 38773980, 2024).
spinal muscular atrophy (1 paper, 2025). A motor neuron disease that affect the muscles, and characterized by muscle weakness and atrophy resulting from progressive degeneration and irreversible loss of the anterior horn cells in the spinal cord (i.e., lower motor neurons) and the brain stem nuclei. "While females retained two of the signals in the main analysis (CHRNA5 and IREB2), males had a single new signal related to a gene involved in spinal muscular atrophy (FGFBP3)." (PMID 40074595, 2025).
steatosis (1 paper, 2025). Increased lipid within the cytoplasm of cells. "Pyrrolidine dithiocarbamate treatment reduced the degree of liver tissue damage caused by overexpression of IREB2 and effectively improved microvesicular steatosis." (PMID 39910919, 2025). "Overexpressing IREB2 aggravated steatosis in the form of inflammatory infiltration, increased the size of fat droplets in the liver, and promoted increased lipid accumulation." (PMID 39910919, 2025).
tumor (43 papers, 2010 to 2025). "KLF14 exerts its anti-tumor function by inhibiting Iron-responsive element-binding protein 2 (IRP2), which then causes transferrin receptor-1(TfR1) downregulation and ferritin upregulation on the basis of IRP-IREs system." (PMID 36600258, 2023). "Meanwhile, ACO1 and IREB2 regulate autophagy-linked ferroptosis along with immune cell invasion in the tumor microenvironment in KIRC patients." (PMID 36059676, 2022). "The research by Yao and co-workers also indicates the protective role of IREB2 for ICC, with higher IREB2 expression in tumor tissue linked to better overall survival." (PMID 37509299, 2023). "Still, further research into the apparent modulatory mechanisms along the functions of ACO1, IREB2 in tumor proliferation, metastasis, and immunological invasion is required." (PMID 36059676, 2022). "After the purity of the tumor was adjusted, ACO1 along with IREB2 expressions was remarkably linked to most immune markers in various kinds of immune cells in KIRC." (PMID 36059676, 2022). "When using the TIMER data resource, we noticed that the ACO1 and IREB2 contents were strongly accompanied with 33 of 38 T-cell biomarkers in KIRC after adjusting for tumor purity." (PMID 36059676, 2022). "Insufficiently, the tangible role of ACO1 and IREB2 in the tumor-immune microenvironment still requires further in-depth investigation." (PMID 36059676, 2022). "We assessed the links between ACO1 and IREB2 and immune invasion by using the accomplished data resource CIBERSORT, which reflects the influences of ACO1 and IREB2 on the tumor microenvironment (TME)." (PMID 36059676, 2022). "Incubation of ferroptosis inhibitors ferrostatin-1 (Fer-1) or knockdown of iron-responsive element-binding protein 2 (IREB2) notably weakened curcumin-induced anti-tumor effect and ferroptosis in A549 and H1299 cells." (PMID 36712505, 2022). "Recently, studies on mouse models showed that overexpression of IREB2 promoted the growth of tumor xenografts in nude mice." (PMID 26310313, 2015). "In addition, the authors have noticed that the unique conserved insert of 73 amino acids of IREB2 mammalian protein, contributes to IREB2 pro-oncogenic potential and is essential for accelerated tumor growth." (PMID 26310313, 2015). "This suggests potential dual functionality: IREB2 may promote early carcinogenesis yet exert tumor‐suppressive effects in established malignancies.​ IREB2 regulates intracellular iron homeostasis by binding iron‐responsive elements (IREs) on ferritin transcripts and iron metabolism‐related genes." (PMID 41377765, 2025). "The tumor suppressor OTUD1 interacts with and promotes deubiquitination of IREB2 (iron-responsive element-binding protein 2), stabilizing IREB2 and activating downstream TFRC gene expression." (PMID 41425599, 2025). "Further GEPIA analysis revealed Decreasing naïve B cells but increasing memory/plasma cells from normal, adjacent normal and tumor tissue, and increasing CD27/IREB2 in memory/plasma cells across these tissues." (PMID 41377765, 2025). "Significant positive correlations with GPX4 (ferroptosis), ACSL4 (fatty acid metabolism), SOD2 (antioxidant), HIF1A (tumor growth and metastasis), FAT1 (fatty acid metabolism) and IREB2 (Iron-responsive element)." (PMID 38206305, 2024). "Regarding the tumor stage, a remarkable decrease in ACO1 and IREB2 expression was watched in KIRC patients in stages I, II, III, and IV." (PMID 36059676, 2022). "In different tumor stages, low ACO1 expression was accompanied with worse OS, DSS, and PFI only in stage 1 and 3 patients with KIRC, while low IREB2 expression was strongly accompanied with worse OS in stage 1,worse DSS in stage 3, and worse PFI in stage 1 and 3 patients with KIRC." (PMID 36059676, 2022).